PTH (parathyroid hormone)
Diseases named in the same sentence as PTH in open-access papers (continued):
Sharing a sentence is not in itself a finding about the gene and the disease.
Hypercalcemia (continued). "Among these causes is hypovitaminosis D, thereby justifying the greater need for supplementation in NHPT patients compared with hypercalcemic PHPT, in which it is sufficient to highlight the inappropriate secretion of PTH in the setting of hypercalcemia regardless of 25(OH)D levels." (PMID 39963179, 2024). "The diagnosis of a parathyroid mass was suspected by the analytical finding of PHPT (hypercalcemia and elevated PTH) and later confirmed by ultrasound (non-invasive and low-cost procedure) and 99mTc-Sestamibi scintigraphy (sensitivity of 90% in detecting parathyroid adenomas)." (PMID 36606108, 2023). "However, in PHPT due to depressed CaSR expression onset, the feedback mechanism between calcium and PTH is disrupted so that hypercalcemia fails to block PTH secretion, thereby aggravating the PHPT symptoms." (PMID 36755240, 2023). "The PTH level however was low and there were no metastases, so the authors speculated that the patient had PTHrP-mediated hypercalcemia." (PMID 37358786, 2023). "In adults, the conventional management uses bisphosphonates, with a preference to alendronate, to improve Bone Mass Density (BMD), since it does not alter serum calcium and PTH concentration; and in an acute setting in case of symptomatic severe hypercalcemia, calcimimetics are combinate." (PMID 36090548, 2022). "A possible explanation for missed diagnoses in patients with hypercalcemia and inappropriately nonsuppressed PTH between 50 and 65 pg/mL could be they were not identified because their PTH levels were within the reference range." (PMID 36574247, 2022). "Since we observed in a subgroup of patients with reported levels of serum 1,25(OH)2D3 and parathyroid hormone (PTH) that the majority of these patients showed a suppressed PTH level, independent of serum 1,25(OH)2D3 levels, a PTH-independent but immune-stimulated hypercalcaemia is assumed." (PMID 36427118, 2022). "Cinacalcet in pediatric HPT can control hypercalcemia and PTH without significant side effects." (PMID 36090548, 2022). "Early intervention of elevated parathyroid hormone levels may lead to better graft outcomes, even without overt hypercalcemia." (PMID 35710357, 2022). "However, there was no significant improvement in cardiac function, but obvious hypercalcemia appeared in these patients, and mild to moderate elevation of PTH was considered to be an adaptive response." (PMID 36267284, 2022). "Interestingly, not all vitamin D analogs have the same effect on lowering PTH levels, and their potential to induce hypercalcemia is different." (PMID 36501215, 2022). "No participant had hypercalcemia, renal stones, or suppressed parathyroid hormone." (PMID 36235600, 2022). "It is unclear why patients with unexplained hypercalcemia did not undergo measurement of PTH." (PMID 36574247, 2022). "Therefore, this retrospective cohort study of 892 kidney transplant patients aimed to identify the impact of elevated PTH levels without hypercalcemia on kidney-graft outcomes." (PMID 35710357, 2022). "In patients with high clinical suspicion of PHPT, there may be an indication to obtain a PTH level in the absence of hypercalcemia, as this can represent early disease or a normocalcemic variant of PHPT." (PMID 34722014, 2021). "This PTH-mediated hypercalcemia inhibited EAE development in female, but not male mice." (PMID 34046214, 2021). "False-negative results in choline/methionine studies may occur in cases of moderate hypercalcemia and non-elevated PTH serum levels (so-called “abnormally normal serum PTH level)." (PMID 33839893, 2021). "Familial hypocalciuric hypercalcemia (FHH) and the use of certain medications, such as lithium, could mimic PHPT presentations and should be considered in the differential diagnoses of hypercalcemia with non-suppressed PTH." (PMID 34736428, 2021).
Hypercalcemia (continued). "Due to concerns about hypercalcemia and oversuppression parathyroid hormone (PTH), a synthetic vitamin D analogue (paricalcitol), a noncalcium-containing phosphate binder (sevelamer), and a calcimimetic (cinacalcet) have entered the market since 1998, 1998, and 2004, respectively." (PMID 34853790, 2021). "We found evidence of PTH transcription in both the original rectal specimen and in the fibular biopsy taken after onset of hypercalcemia, but not in the fibular biopsy that was taken before onset of hypercalcemia, nor in ipsilateral inguinal lymph node metastasis." (PMID 33413267, 2021). "Cinacalcet has been shown to lower PTH and serum calcium and may be a valuable option in the presence of significant hypercalcemia due to PHPT if surgery is not an option." (PMID 33918966, 2021). "The European Society of Endocrine Surgeons stated in a consensus report of 2015, that subtotal PTx was specifically indicated when medical treatment fails to correct metabolic parameters meaning hypercalcemia, hyperphosphatemia, but interestingly also PTH > 85 pmol/L." (PMID 33892650, 2021). "Our clinical experience is consistent with this, as we have not observed hypercalcemia, renal insufficiency, hypercalciuria, undetectable serum parathyroid hormone concentrations or any other toxicity in patients with serum 25(OH)D3 concentrations ranging from 202 ng/mL to 384 ng/mL." (PMID 33947070, 2021). "PTH is involved in many pathological conditions in which calcium and phosphorus metabolism is imbalanced; among these, primary hyperparathyroidism, renal secondary hyperparathyroidism (RHPT), nutritional secondary hyperparathyroidism, and hypercalcemia of malignancy." (PMID 34827832, 2021). "Repletion of vitamin D in such patients is recommended which may lead to reduction of PTH levels and bone turnover while hypercalcaemia is reassuringly not exacerbated." (PMID 31797261, 2020). "Creatinine clearance in Trpc1–/– mice was comparable to that in WT mice, indicating that renal failure could not have accounted for the hypercalcemia and elevated PTH levels seen in Trpc1–/– mice." (PMID 32213715, 2020). "Also, cinacalcet treatment is usually titrated to improve hypercalcemia to a level that is less harmful to patients, but not toward the normalization of PTH level." (PMID 32621588, 2020). "PTH levels were significantly higher in 7-month-old homozygous mutant males and inappropriately high in 7-month-old homozygous mutant females (because they were not suppressed by hypercalcemia as expected in normal physiology)." (PMID 32213715, 2020). "Calcimimetic treatment was suggested by the consultant endocrinologist on the account of the need for correcting hypercalcemia (contraindications to steroids; parathyroidectomy not accepted by the patient; unsuppressed PTH levels) in the wait for response to antitubercular treatment." (PMID 32075103, 2020). "Regarding the two patients without a diagnosis of hyperparathyroidism prior to the surgery (patients #1 and #2), one of them (patient #1) did not have PTH levels measured before surgery, however during post-operative follow up she was diagnosed with hyperparathyroidism and hypercalcemia." (PMID 31708875, 2019). "Following this second surgery, her PTH levels did not normalize and she still had hypercalcemia." (PMID 31708875, 2019). "Three out of 10 (30%) patients had an endocrine paraneoplastic syndrome due to tumor-produced adrenocorticotropic hormone (ACTH), resulting in ectopic Cushing’s disease, parathyroid hormone-related protein (PTH-rp) resulting in severe hypercalcemia and dopamine without clinical sequelae." (PMID 30953466, 2019). "There was no incidence of PTH-dependent hypercalcemia in examined group of patients." (PMID 29599854, 2018). "Although it is characterised by a positive family history, hypercalcemia and hypocalciuria accompanied by normal or marginally elevated PTH, some patients may not demonstrate all these features." (PMID 28443817, 2017).
Hypercalcemia (continued). "Vitamin D supplementation resulted in worsening of hypercalcemia without reduction in PTH levels." (PMID 28732535, 2017). "Opposite to vitamin D receptor activator (VDRA), nutritional vitamin D compounds are unlikely to induce hypercalcemia using a normal regimen because its 1α-hydroxylase activation is regulated by PTH, FGF-23 and 24-hydroxylase.Therefore, a serum 25(OH)D level up to 100 ng/mL is considered safe." (PMID 28346348, 2017). "In the hypercalcemias of malignancy, such elevations of PTH are virtually never seen." (PMID 28900835, 2017). "Laboratory investigations confirmed hypercalcemia but revealed a constellation of primary hyperparathyroidism and not hypercalcemia of malignancy; in the latter condition, a suppressed rather than an increased value of parathyroid hormone would have been expected." (PMID 28476174, 2017). "In the lynx with subclinical toxicosis this moderate degree of hypercalcemia was not surprising and the absence of marked hypercalcemia may be explained by the hormonal adjustments after chronic exposure to high doses of vitamin D as backed up by low PTH." (PMID 27243456, 2016). "The increase in calcitriol found in the captive lynx without renal disease may be related to the moderate hypercalcemia and non-significant decrease in PTH, which would be insufficient to block calcitriol production." (PMID 27243456, 2016). "Since PTH levels are not proportionately high, the poor control of hypercalcemia may be partly a result of PTHrP." (PMID 27998296, 2016). "FHH is a highly penetrant autosomal dominant condition characterised by lifelong non-progressive mild-to-moderate hypercalcaemia, normal (in ~80% of patients) or mildly raised serum PTH levels (in ~20% of patients), and low urinary calcium excretion (in ~95% of patients)." (PMID 27647839, 2016). "In two of the cases, the reason for hypercalcemia was not sought, in one case hypercalcemia was found to be PTHrP-mediated, and in the last case hypercalcemia was found to be calcitriol-mediated (not secondary to elevated PTH or PTHrP)." (PMID 26499069, 2015). "Injections with PTH once or twice a day have not been shown consistently to lower urinary calcium and intermittent hypercalcemia may develop in the hours following an injection." (PMID 25101193, 2014). "At the time of hypercalcemia, intact PTH was appropriately suppressed, and PTHrP was not elevated." (PMID 23476827, 2013). "However, other potential mechanisms may also play a role, such as mild systemic inflammation, which has been described in both hyperparathyroidism and hyperuricemia, or the direct involvement of hypercalcemia, regardless of PTH." (PMID 40710544, 2025). "PTH plasma concentration is increased in most patients with primary hyperparathyroidism and is lower than normal or close to the lower limit of the reference range in most patients with hypercalcemia of nonparathyroid origin, including neoplastic hypercalcemia." (PMID 40290309, 2025). "However, the resolution of hypercalcemia after the cessation of almond milk consumption and the lack of recurrence constitute strong evidence against PTH-rP–induced hypercalcemia, Interestingly, metabolic alkalosis, a common feature in milk-alkali syndrome, was not present in this case." (PMID 40123931, 2025). "In turn, a solitary elevation of PTH without concomitant hypercalcemia may not only result from secondary hypoparathyroidism (caused by vitamin D deficiency and/or chronic renal failure), but also from primary hyperparathyroidism at an initial/compensated state." (PMID 39636417, 2024). "Whether these effects were due to hypercalcemia or PTH therapy itself was not investigated." (PMID 37335755, 2023). "Thus, for severe and progressive secondary hyperparathyroidism (SHPT) in CKD G5D, calcitriol or vitamin D analogues should be considered, with an initially low dose, independent of the initial PTH concentration, and then titrated based on the PTH response, and hypercalcaemia should be avoided." (PMID 35065601, 2022).
Hypercalcemia (continued). "However, a high level of PTH alone is not generally a factor in making therapeutic decisions because it is not known whether high PTH levels without hypercalcemia may adversely affect kidney-graft function after KTx." (PMID 35710357, 2022). "Therefore, PTH levels may be lower than anticipated and the finding of hypercalcemia in the presence of a non-suppressed PTH level is suspicious for a diagnosis of PHPT during pregnancy." (PMID 34209340, 2021). "Hypercalcemia may be attributed to parathyroid hormone or not." (PMID 33718400, 2021). "Given the increasingly reduced cost of genetic testing and the cost of follow up and unnecessary surgery, it may prudent to include genetic testing for FHH early on in patients with mild non-progressive PTH-dependent hypercalcemia despite negative family history and even positive localization." (PMID 33499837, 2021). "Serum calcium, phosphorus, intact PTH, and activated vitamin D requirements (paricalcitol) were similar in the control and intervention arms through the trial, and no episodes of sustained hypercalcemia occurred in either group during the study (see RawData S1)." (PMID 25296334, 2014). "PTH is remeasured after 1 month of calcitriol, and if not significantly suppressed, the dosage of calcitriol may be incrementally (5 ng/kg) increased, again checking for hypercalcemia as above after any increase in the calcitriol dose." (PMID 23566108, 2013). "In mice with CKD, intestinal Cyp24a1 deletion decreased PTH and FGF23 without precipitating hypercalcemia." (PMID 39688907, 2024). "Although it is unusual, in patients who present with hypercalcemia due to NET, it would be better to consider ectopic production of PTH whenever high PTH levels are present with no parathyroid-related cause." (PMID 37670372, 2023). "Nevertheless, this was not in line with the observed hypercalcemia, elevated levels of FGF23 and increase in 1,25-dihydroxy vitamin D3, which all should have suppress PTH level." (PMID 26566277, 2015). "For example, if one experienced simultaneous hypercalcaemia and hyperphosphataemia then without an inhibitory input from PO4, the high Ca2+o could maximally suppress PTH secretion abrogating the phosphaturia needed to resolve the hyperphosphataemia." (PMID 37064904, 2023). "If there is no improvement in serum parathyroid hormone (PTH) level, the dose could be increased up to a maximum of 20 μg, with monitoring for the development of hypercalcemia." (PMID 32181403, 2020).
Hypocalcemia (1,112 papers, 2002 to 2026). An abnormally decreased calcium concentration in the blood. "Serum albumin, magnesium, free calcium, vitamin D, and PTH levels, as well as kidney function, must be assessed to understand the cause of hypocalcemia." (PMID 41601884, 2026). "From treatment to follow-up, the lack of indirect suppression due to reduced calcium and phosphate absorption appears linked to the worsened hypocalcemia observed in 24% of patients at follow-up and sustained PTH elevation at 17%." (PMID 40663633, 2026). "Hypoparathyroidism is a rare endocrine disorder characterized by deficient secretion of parathyroid hormone (PTH), resulting in hypocalcemia, hyperphosphatemia, and impaired mineral homeostasis." (PMID 41993986, 2026). "In conditions with hypocalcemia associated with hypomagnesemia, inadequate low or inappropriate normal PTH secretion has been observed, referred to as paradox inhibition of PTH secretion associated to hypomagnesemia." (PMID 40740723, 2025). "In CKD patients, hyperphosphatemia associated with calcitriol deficiency leads to hypocalcemia, which in turn stimulates PTH secretion, ultimately resulting in secondary hyperparathyroidism." (PMID 41301699, 2025). "A suppressed or inappropriately low PTH level in the presence of hypocalcemia confirms hypoparathyroidism as the underlying cause." (PMID 40717880, 2025). "In SHPT, denosumab increases femoral neck and lumbar spine BMD and decreases PTH; however, it carries the risk of severe hypocalcemia." (PMID 40177730, 2025). "This is a post-PTx entity caused by the fast reduction of PTH levels with subsequent bone remineralization leading to severe hypocalcaemia." (PMID 40283231, 2025). "Collectively, this outlines a clear pathophysiological cascade which is as follows: Prolonged AED use → vitamin D deficiency → hypocalcemia → compensatory PTH elevation → increased bone turnover → risk of fragility fractures." (PMID 41210018, 2025). "Risk factors for the development of hypocalcemia were: high preoperative levels of alkaline phosphatase and parathyroid hormone, low level of preoperative corrected calcium, and younger age." (PMID 40517023, 2025). "This study aimed to evaluate factors associated with hypocalcemia at 24 h after total thyroidectomy, identify independent predictors, and assess the reliability of early PTH measurement in determining supplementation needs." (PMID 41595598, 2025). "In published studies, elevated preoperative ALP and PTH levels were often reported to be closely associated with postoperative hypocalcemia, while other less common risk factors include longer dialysis duration, advanced age, and hyperkalemia." (PMID 41367906, 2025). "Our study concluded that pre‐operative corrected calcium, ALP, PTH, and age are risk factors for hypocalcemia development post‐parathyroidectomy." (PMID 40517023, 2025). "Hypocalcemia causes parathyroid hormone (PTH) release and calcitriol production, which raise intracellular calcium ([Ca2+]i) in vascular smooth muscle cells (VSMC) by activating L-type calcium channels." (PMID 40290310, 2025). "Gain-of-function mutations in the TM6–TM7 transmembrane region of CASR drive ADH1 by increasing receptor sensitivity to calcium, lowering the PTH suppression threshold, and causing hypocalcemia with low PTH and hypercalciuria." (PMID 41155848, 2025). "Postoperative PTH suppression leads to enhanced osteoblastic activity, increasing the risk of hypocalcemia." (PMID 41450586, 2025). "Pseudohypoparathyroidism with its types PHP1A, PHP1B, and PHP1C, was first described by Albright as a disorder caused by resistance of target tissues to PTH and characterized by hypocalcemia and hyperphosphatemia." (PMID 40177730, 2025). "Secondary hyperparathyroidism, as seen here (elevated PTH), arises from 1,25 Vit D deficiency, causing transient hypocalcemia." (PMID 40951211, 2025).